CD4 (CD4 molecule)
Diseases named in the same sentence as CD4 in open-access papers (continued):
Sharing a sentence is not in itself a finding about the gene and the disease.
tumor (continued). "This approach encourages macrophages to phagocytose irradiated tumor cells, enhances antigen cross-presentation, and ultimately boosts the infiltration and activity of CD8+ and CD4+ T-cells." (PMID 40860882, 2025). "However, the role of LTβR in CD4+ T cell differentiation and anti-tumor activity remains unclear." (PMID 40436857, 2025). "Although the tumor killing effect is mainly attributable to cytotoxic CD8+ T cells and natural killer (NK) cells, CD4+ T cells also play an essential role in inducing a durable antitumor immunity through multiple mechanisms." (PMID 40759573, 2025). "Our results revealed that the combination of gM with the TCL/DCV significantly increased the levels of NK cells, as well as CD4+ and CD8+ T cells, both in the spleen and the tumor tissue." (PMID 40426190, 2025). "In individuals with CAC, disturbances in CD3+ T cell proliferation and CD4+/CD8+ ratios amplify inflammatory responses and intestinal lesions, thereby facilitating tumor immune evasion." (PMID 40734913, 2025). "In contrast, within the Tumor-Immune enriched neighborhood (comprising ~50% tumor and ~50% stromal/immune cells), CD8+T- cells were enriched for Granzyme B and PD-1 whereas CD4+T- cells in this neighborhood were enriched for ICOS and PD-1." (PMID 41254766, 2025). "This, in turn, leads to a diminution of CD8+ and CD4+ T cells within the TME, ultimately accelerating tumor progression." (PMID 40230836, 2025). "Specifically, CD4+ and CD8+ T cell density increased 14-fold and 12-fold, respectively, compared to the screening tumor biopsy." (PMID 39753970, 2025). "The CIBERSORTx results showed that CD4 T memory cells, CD8 cells, and macrophages were enriched in tumor tissue." (PMID 40692710, 2025). "Immune profiling of CBL0137-treated mice revealed significantly enhanced tumor-specific immune responses and increased proportions of tumor infiltrating effector CD8+ T cells, CD4+ T cells, and NK cells." (PMID 39706891, 2025). "Flow cytometric analysis of tumor-derived single-cell suspensions revealed significantly increased infiltration of CD45+ immune cells, CD3+ T cells, and both CD4+ and CD8+ T cell subsets in the CAR-M group." (PMID 41388305, 2025). "For instance, tumor regions enriched with Fusobacterium nucleatum often exhibit reduced infiltration of CD4+ and CD8+ T cells, indicating suppression of anti-tumor immunity." (PMID 41396345, 2025). "The T cell Immune-receptor with immune-globulin and ITIM domain (TIGIT) is a coinhibitory immune-modulatory checkpoint receptor, present on T cells CD8+, CD4+, T regs, and NK cells, which binds to ligands CD112 and CD115 on tumor cells and APCs." (PMID 41514645, 2025). "In tumor samples from patients with NSCLC treated with ICIs, high CD4+ cell densities in the tumor cores correlated with favorable clinical outcomes, highlighting the clinical utility of our noninvasive PET imaging approach." (PMID 40561008, 2025). "CD4+ T cells, in addition to providing help, can secrete cytokines and deliver costimulatory signals to sustain and amplify CD8+ T-cell-mediated tumor killing." (PMID 40573908, 2025). "Much more work is needed to understand how to augment presentation of tumor antigens to CD8+ T cells by such novel APCs in the TME, including coordinated downstream CD4+ and CD8+ anti-tumor responses in the setting of lung cancer progression." (PMID 41479781, 2025). "When DCs activated by NTP were injected into the peritoneal cavity of mice with Lewis Lung cancer, they promoted the infiltration of CD4+ and CD8+ T cells into the tumor microenvironment, boosting the adaptive immune response and reducing tumor growth." (PMID 40431612, 2025). "Normally neutrophils and Treg cells are considered to be pro-tumor progression cells, while CD4+ and CD8+ T cells are cells that inhibit tumor progression." (PMID 39963143, 2025).
tumor (continued). "Anti-tumor immune cells primarily include effector T cells (such as cytotoxic CD8+ T cells and effector CD4+ T cells), natural killer cells (NK), dendritic cells (DC)." (PMID 40013144, 2025). "This change not only enhances the infiltration of cluster of differentiation 4+ (CD4+) and CD8+ T cells but also restores major histocompatibility complex (MHC) class I expression on tumor cells, facilitating better recognition and destruction by T cells." (PMID 40061139, 2025). "Collectively, our findings demonstrate that both CD4+ and CD8+ T cells in the anti-tumor response induced by CR108 + OVA immunizations." (PMID 40606756, 2025). "The frequencies of CD4+ T cells, CD8+ T cells, and M1 macrophages were increased in tumor tissues, as confirmed by immunohistochemical analysis." (PMID 39792573, 2025). "Mature DCs present tumor antigens to CD8+ cytotoxic T cells via MHC-I and to CD4+ helper T cells via MHC-II, inducing a specific anti-tumor immune response." (PMID 40420798, 2025). "The iC2 has a high Tumor Immune Dysfunction and Exclusion (TIDE) score, representing an immune-suppressive state characterized by elevated levels of CD8+, activated CD4+ cells, and PD-L1 expression, resulting in poor outcomes." (PMID 40332491, 2025). "This suggests that CFRI-mediated PTT evidently promotes the differentiation of immature T cells into CD4+ and CD8+ T cells, enhancing immune surveillance and tumor elimination and potentially preventing tumor progression, recurrence, or metastasis." (PMID 40040955, 2025). "The numbers and percentages of tumor-infiltrated suppressor cells such as MDSCs (CD11b+Gr-1+) and Tregs (CD45+CD4+FoxP3+) also remained at a similar level." (PMID 40134427, 2025). "Tumor vaccines activate adaptive immunity by delivering tumor antigens to dendritic cells (DCs), inducing antigen-specific CD8+/CD4+ T cell responses and long-term memory." (PMID 40458686, 2025). "The Kras ASO and immRNA combination treatment resulted in significantly higher effector memory CD4+ and CD8+ T cells than all other treatments in the CT26 tumor model." (PMID 40585984, 2025). "Two studies examined the CD4/CD8 ratio in the entire tumor area: one study found a better survival in patients with high CD4/CD8 ratio, but the other study found a worse survival correlated with high CD4/CD8 ratio instead." (PMID 39904885, 2025). "α2 receptor agonists can directly activate macrophages and promote the recruitment and activation of CD4+ and CD8+ T lymphocytes within the tumor micro-environment." (PMID 40161377, 2025). "The cluster 1 showed lower infiltration of anti-tumour immune cells such as CD8 T cells and Th1-like CD4 T cells, whereas higher infiltration of pro-immune evasion cell types such as M2 macrophages and neutrophils in comparison with other clusters." (PMID 40657372, 2025). "A phase Ib trial demonstrated durable neoantigen-specific CD4+ and CD8+ T cell responses with significant tumor reduction in metastatic melanoma lesions." (PMID 40573922, 2025). "While immunomodulatory strategies typically focus on bolstering tumor-infiltrating CD8+ T cell activity, CD4+ T cells also significantly influence the TME by secreting cytokines that enhance CD8+ T cell infiltration." (PMID 40486875, 2025). "Specifically, IFNγ and TNFα were identified as key upstream regulators that dictate the activation status of eosinophils facilitating CD4+ and CD8+ T cell infiltration and anti-tumor immunity." (PMID 40050933, 2025). "F. nucleatum can inhibit the aggregation of tumor stromal CD3+ lymphocytes and CD3+CD4+CD45RO+ cells, key components of T-cell-mediated immunity." (PMID 39995663, 2025). "As CD4+ T cells mainly perform immune regulatory functions and CD8+ T cells mainly perform direct tumor-killing functions, it is efficient for tumors to combat CD8+ T cells stronger than other immune cells." (PMID 40002895, 2025).
tumor (continued). "We further showed an enrichment of CD4+ and CD8+ T cells as well as total and CD80+ macrophages, confirming immune cell infiltration in tumours treated with IL‐12 minicircle‐loaded RBCEVs." (PMID 39193804, 2025). "Histopathology confirmed complete tumor ablation in 9 of 10 cases, with immune infiltrates, predominantly CD3+ lymphocytes (CD4+ and CD8+ equally represented)." (PMID 41428121, 2025). "CD4+ T cells secrete cytokines such as IFN-γ and TNF, which directly limit tumor growth and modulating the immunogenicity and vascularization of the tumor microenvironment (TME)." (PMID 40458394, 2025). "CXCL17 promotes the infiltration of CD4+ T cells and CD68+ immune cells into the tumor microenvironment, thereby accelerating tumor growth and metastasis." (PMID 41459506, 2025). "CD4+ T cells pre-activated with an anti-CD3 antibody and cultured with tumor cell-derived EVs induced a substantial expansion of CD4+CD25+ forkhead box P3 (FOXP3+) Tregs." (PMID 40182121, 2025). "In anti-cancer immunity, defects in antigen processing and presentation represent a key mechanism by which tumor cells escape surveillance by both cytotoxic CD8+ T cells and CD4+ T helper cells 25-27." (PMID 41281743, 2025). "We also examined the relationship between GALNT7 staining and tumor cell PD-L1 positivity, Tn antigen H-score, and infiltration of CD8+ TILs, CD4+ TILs, Foxp3+ TILs, and CD163+ macrophages, stratified by MMR/MSI status." (PMID 40824763, 2025). "The balance among CD4+ helper T cells (Th), CD8+ cytotoxic T cells (Tc), and regulatory T cells (Tregs) is a central determinant of tumor immune dynamics and clinical outcomes." (PMID 41375696, 2025). "In contrast, administering CCL20 via intratumoral injection in subcutaneous HCC mouse models restored tumor growth, reduced the CD8+ T cell infiltration, increased the frequency of CD4+CD25+Foxp3+ Tregs and CCR6+ Tregs in shGal1 tumors." (PMID 39853961, 2025). "The results indicated a marked increase in glucose uptake in spermidine‐exposed TILs, observable across both CD4+ and CD8+ tumor‐infiltrating T cells subsets." (PMID 41179971, 2025). "The flow cytometry analysis of the tumor-draining lymph nodes showed a significant expansion of CD8+ T cells and a decrease in CD4+ T cells, whereas in the spleen, we observed similar changes in the CD8+ population." (PMID 40361381, 2025). "CD4+CD25+Foxp3+ Tregs are recruited and expanded in tumors and constitute an important mechanism utilized by tumor cells to evade protective immunity and support metastatic growth." (PMID 40244064, 2025). "Tumor vasculature and microenvironment changes were analyzed via immunohistochemistry (CD31, α-SMA, CD4, CD8)." (PMID 41488668, 2025). "In contrast, neutrophils and CD4+ T cells showed negative correlations, but these associations were not statistically significant, indicating that immune activation rather than suppression predominantly characterizes the high-risk group’s tumor microenvironment." (PMID 41227385, 2025). "Despite the high prevalence of CD4+ and CD8+ T cells, immune checkpoint blockade therapies, designed to enhance anti-tumor immune responses, have demonstrated limited efficacy in ovarian cancer." (PMID 41029436, 2025). "The elevation of PNI is mechanistically linked to enhanced tumor-infiltrating lymphocyte (TIL) intensity, particularly CD4+ and CD8+ T cells, which are critical for anti-tumor immune responses." (PMID 40491917, 2025). "In the MC38 animal model, it inhibited tumor growth, increased CD8+ lymphocyte infiltration in the tumor, and stimulated IFN-γ production by CD4+ and CD8+ T cells in lymph nodes and spleen." (PMID 40574024, 2025). "Transferred CD4+ and CD8+ T cells underwent several rounds of proliferation in tumor-DLNs and tumor-non draining lymph nodes (tumor-NDLNs) on day 10 after infusion into sublethally irradiated mice." (PMID 40386771, 2025).
tumor (continued). "CD4+ T cells have a critical role in TME of BC, and their functions in anti-tumor immunity are increasingly recognized as more versatile than previously thought." (PMID 40177538, 2025). "While this area has not been extensively studied, emerging evidence nevertheless suggests that similar changes in CD4 + and CD8 + dynamics point to improved cytotoxic effector functions and are correlated with favourable outcomes and tumour response." (PMID 40341577, 2025). "In tumor tissues, the density of FAM111B-positive cells was significantly positively correlated with the density of immune cells, including CD8+ T cells, CD4+ T cells, Tregs, CD4+ Teff cells, M1 macrophages, M2 macrophages, neutrophils, and DCs (all p < 0.05)." (PMID 40564014, 2025). "The dynamics of CD4+ and CD8+ T cell presence and their functional status in the TME of DLBCL are critical for understanding tumor immunology and refining treatment approaches." (PMID 40599139, 2025). "In AD/Fn models, the CD4+ and CD8+ T cells in NM@PLGA‐MTI‐OXA group were ≈2.43‐fold and ≈2.69‐fold of that in Fn group, suggesting an up‐regulation of tumor immunity." (PMID 40433907, 2025). "The downregulation of MYOSLID correlates with increased immune cell infiltration, especially the elevation of CD4+ and CD8+ T cell populations, indicating its potential role in modulating the tumor immune microenvironment." (PMID 40149492, 2025). "As anticipated, radiation therapy resulted in an increase in the proportion of CD4 T cells that were CD25+FoxP3+ Treg and an overall increase in Treg as a proportion of live cells in the tumor." (PMID 41417245, 2025). "As a result, CD4+ T cells exhibited increased IL-2 production, CD8+ T cells secreted more IFN-γ, and overall tumor growth was significantly reduced." (PMID 40940834, 2025). "Combined CB + miR + R/SLN-CSW suppressed IL-17, G-CSF, and CXCL1, increased infiltration of CD4+ and CD8+ T cells, reduced Tregs and M2-TAMs, and inhibited tumor growth in CT-26 bearing mice." (PMID 41304839, 2025). "Tumor growth was not only significantly reduced, but this was accompanied by a significant increase in the infiltration of IFN-γ+ CD4 and CD8 T cells into the tumor." (PMID 39702544, 2024). "As with PDL-1 and TIM-3, the LAG-3 receptor is also present in myeloid and lymphoid cells, including NK cells and DCs and CD4+ T-cells, regulatory T-cells, and CD8+ tumor-infiltrating cells." (PMID 38256021, 2024). "The induction of a balanced CD4+ and CD8+ T cell response by ELI-002 2P is likely to support the development of a multi-pronged anti-tumor defense." (PMID 38195752, 2024). "Activation and proliferation of CD4+ T and CD8+ T cells in peripheral blood and within the tumor also significantly increased." (PMID 38384806, 2024). "Then we used Loupe Browser 7.0 to group spots with gene characteristics (log2 count > 0) of CD68 or CD4 with CTLA4 as THC, and spots with gene characteristics of CD3D or CD3E or CD3G as tumor immune cells." (PMID 39499374, 2024). "In addition, flow cytometry (FCM) analysis of CD39 (encoded by ENTPD1) in HGSC samples revealed a greater expression in tumor-infiltrating Tregs compared to CD4+ and CD8+ effector T cells, indicating that Tregs may account in a large part for ENTPD1 expression." (PMID 39013886, 2024). "The Akt downregulates Treg cells while upregulates CD4+ and CD8+ tumor-infiltrating lymphocytes (TILs), leading to IFNγ expression and thereby inducing an anti-tumor immune response." (PMID 38715072, 2024). "We thus analyzed the number of CD4+ and CD8+ T‐cells in lymph nodes from tumor bearing mice following different treatments." (PMID 39553435, 2024). "Findings have indicated that CAR-T cells crafted from CD4+ and CD8+ TN and TCM subsets exhibit heightened tumor-fighting potency and proliferation compared to those originating from TEM." (PMID 39409959, 2024). "IHC staining using antibodies against CD3, CD4, and CD8 was performed on tumor tissues to assess immune cell infiltration." (PMID 39459546, 2024).
tumor (continued). "Subsequently, a significant elevation in Tregs cells (CD4+ FOXP3+) and a reduction in effector cells (CD8+/CD19+) in the tumor tissues of NSCLC clinical specimens from 40 patients undergoing combined chemotherapy and immunotherapy was observed." (PMID 38981044, 2024). "As antigen-presenting cells, DCs process and present antigens via MHC-like molecules to CD4+ and CD8+ T cells, thereby initiating a robust immune response against tumor cells." (PMID 39174509, 2024). "Specifically, we examined the presence of CD4+, CD8+, CD20+, CD68+, and CD163+ cells within the tumor microenvironment." (PMID 38288307, 2024). "The importance of CD4 and CD8 T cells for anti-tumour immunity is well-defined and extensively reviewed elsewhere." (PMID 38223410, 2024). "It was also found that there exists a subset of T cells expressing CD4+CD25-CD69+Foxp3-LAP+, which inhibits T cell proliferation and promotes tumor immune escape by secreting TGF-β." (PMID 39703499, 2024). "Specific bacterial immunotherapy can result in enhanced tumor-specific CD4 and CD8 T cell response, leading to T cell-dependent tumor immunity and sometimes even long-term tumor specific immunity." (PMID 38515744, 2024). "Intriguingly, BEV@BMDCs induced CD4+ T cells and CD8+ T cells to infiltrate in deep layer of tumor tissue." (PMID 39021327, 2024). "CD4+ T cells especially expressed CD134, showing their activation at the tumor site both at the edge of and within the tumor." (PMID 38203786, 2024). "As expected, the proliferation rate of CD4+ T cells and CD8+ T cells in the tumor microenvironment from IFNγ+/− cKO mice were considerably rescued by the deletion of IFNγ." (PMID 38167862, 2024). "We compared the spatial characteristics between Tregs and Tcons and the results showed that CD4+Tregs in TC and CD8+Tregs in both IM and TC were surrounded by more tumor cells." (PMID 39093404, 2024). "Immunofluorescence indicated the CD4+ T cells, CD8+ T cells, and Treg cells were gathered around blood vessels, with only a few infiltrating lymphocytes in the tumor tissue." (PMID 39723389, 2024). "The percentage of activated CD4+ T cells and CD8+ T cells was significantly increased in tumor tissues treated with DEV-AIE." (PMID 38298192, 2024). "To further verify the effect of the LZFPN-90-dependent immune environment, we examined the effect of different treatments on CD4+ and CD8+ T cells in tumor tissue." (PMID 38448544, 2024). "After combing digital pathology with spatial analysis, one unique spatial architecture with CD8+ T and CD4+ T cells enriched neighborhoods is identified and leads to less proximity of CD8+ T cells to the tumor cells, heralding a shorter OS." (PMID 38611111, 2024). "By reducing infiltrated TAMs in PDAC with clodronate liposomes, Yang et al136 found that CD8+ T cell infiltration increased, the number of CD4+ Foxp3+ Tregs decreased, and effector CD8+ T cells were spatially brought closer to tumor cells." (PMID 40458305, 2024). "Our imaging data shows that higher CAF populations in the stromal regions are only able to limit the entry of CD4+ T cells, CD8+ T cells, and plasma B cells into the tumor microenvironment, which results in the creation of an immunosuppressive environment." (PMID 39605357, 2024). "Remarkably, in the tumor tissues of mice implanted with LLC‐shPRPS2 cells, we observed a significant increase in the percentage of CD4+ T cells and CD8+ T cells, along with a notable reduction in the percentage of TAM, M‐MDSC, and PMN‐MDSC." (PMID 38952044, 2024). "In that study, compared to normal breast tissues, tumor tissues exhibited a marked decrease in CD8+ T cells and a marked increase in the proportion of CD4+ and CD4+ and CD8+ T cells expressing PD-1 and CD39." (PMID 39735530, 2024). "Although TAMs were decreased in Slit-knockdown tumors, the overall number of tumor-associated lymphocytes (TALs) was raised by threefold, along with increased CD4+ and CD8+ T lymphocytes inside the tumor." (PMID 39456164, 2024).